RN7SL656P (RNA, 7SL, cytoplasmic 656, pseudogene)
Gene: Miscellaneous RNA gene on chromosome 17 (46,319,679 to 46,319,959, forward strand). Ensembl gene ENSG00000265411.
Homologues: Orthologues: chimpanzee Metazoa_SRP (95% identical), macaque Metazoa_SRP (93% identical), macaque Metazoa_SRP (92% identical), chimpanzee Metazoa_SRP (89% identical), rabbit Metazoa_SRP (68% identical). Paralogues in human: RN7SL199P (100% identical), Metazoa_SRP (99% identical), RN7SL270P (99% identical), RN7SL404P (96% identical), RN7SL1 (85% identical), RN7SL3 (85% identical), RN7SL2 (84% identical), RN7SL45P (82% identical), RN7SL333P (81% identical), RN7SL712P (81% identical), RN7SL804P (81% identical), RN7SL88P (81% identical), and 707 more.